KPNA2 (karyopherin subunit alpha 2)
Diseases named in the same sentence as KPNA2 in open-access papers (continued):
Sharing a sentence is not in itself a finding about the gene and the disease.
osteosarcoma (continued). "Sixty-seven of 81 (82.7%) osteosarcoma, zero of 42 (0%) chondrosarcoma and one of 15 (6.7%) ES samples showed immunoreactivity for KPNA2." (PMID 33176814, 2020). "We detected expression of KPNA2 via immunohistochemical staining in the different osteosarcoma types, including three conventional and two other subtypes." (PMID 33176814, 2020). "In this study, we carried out a comparative analysis of KPNA2 expression profiles in osteosarcoma, chondrosarcoma, ES and several benign bone tumor clinical samples." (PMID 33176814, 2020). "In summary, we found for the first time that KPNA2 immunohistochemical expression was highly sensitive and specific for osteosarcoma compared with chondrosarcoma and ES." (PMID 33176814, 2020). "As such, KPNA2 can serve as a novel biomarker for diagnosing osteosarcoma." (PMID 33176814, 2020). "This study reveals that KPNA2 immunoexpression may be a potential marker for differentiating osteosarcoma, particularly the osteoblastic and chondroblastic subtypes, from chondrosarcoma and ES." (PMID 33176814, 2020). "Therefore, the sensitivity and specificity of KPNA2 immunoexpression were 82.7 and 100%, respectively, in osteosarcoma samples." (PMID 33176814, 2020). "Therefore, the proportion and intensity of KPNA2 expression found in osteosarcomas were obviously stronger than the respective levels in chondrosarcoma and ES samples (P < 0.001)." (PMID 33176814, 2020). "KPNA2 positivity was observed in ten of 13 (76.9%) chondroblastic, two of 6 (33.3%) fibroblastic, three of 4 (75%) telangiectatic and two of 3 (66.7%) giant cell-rich osteosarcoma samples." (PMID 33176814, 2020). "Moreover, despite there being fewer than six fibroblastic, telangiectatic and giant cell-rich osteosarcoma samples, the tendency for positive KPNA2 expression in these subtypes agrees with the results seen in osteoblastic and chondroblastic samples." (PMID 33176814, 2020). "We investigated the expression of KPNA2 protein by immunohistochemistry on paraffin-embedded surgical specimens from 223 patients with malignant and benign bone tumors, including 81 osteosarcomas, 42 chondrosarcomas, 15 ESs, 28 osteoid osteomas, 20 osteochondromas and 37 chondroblastomas." (PMID 33176814, 2020). "Telangiectatic and giant cell-rich osteosarcoma samples were also reactive for KPNA2, but the pattern of staining was generally not as extensive as that in osteoblastic osteosarcomas." (PMID 33176814, 2020).
squamous cell carcinoma (4 papers, 2013 to 2021). A carcinoma arising from squamous epithelial cells. "We found that KPNA2 expression is induced in various proliferative disorders of the skin such as psoriasis, Bowen’s disease, actinic keratosis, squamous cell carcinoma, Paget’s disease, Merkel cell carcinoma, and mycosis fungoides." (PMID 24098495, 2013). "In contrast, there was marked KPNA2 staining in the nuclei and cytoplasm of malignant cells in several skin tumors with different prognoses including Bowen’s disease, actinic keratosis, squamous cell carcinoma (SCC), Paget’s disease, Merkel cell carcinoma, and Mycosis fungoides." (PMID 24098495, 2013).
brain cancer (3 papers, 2015 to 2018). A primary or metastatic malignant neoplasm affecting the brain. "Our results strongly suggest that silencing of KPNA2 might be taken into account when designing new tailored therapeutic approaches for GBM, which remains still an incurable brain cancer." (PMID 30323892, 2018).
ductal carcinoma in situ (3 papers, 2015 to 2022). "Our search of the Oncomine database showed that at the transcriptional level relative to matched healthy breast tissue, the expression of KPNA2 was significantly upregulated in invasive lobular breast carcinoma, ductal breast carcinoma in situ, and invasive breast carcinoma." (PMID 35948941, 2022).
oral squamous cell carcinoma (3 papers, 2022 to 2023). "In oral squamous cell carcinoma, miR-17 functioned as a tumor suppressor via regulating KPNA2/PI3K/AKT axis." (PMID 35536524, 2022). "KPNA2 has been shown to mediate the survival outcomes for oral squamous cell carcinoma patients." (PMID 35860570, 2022).
pancreatic cancer (3 papers, 2013 to 2023). "To explore the clinical significance of KPNA2, we downloaded four independent GEO datasets of pancreatic cancer, including GSE15471, GSE16515, GSE62452, and GSE28735." (PMID 33728352, 2021). "KPNA7 was reported to promote malignant properties of pancreatic cancer cells in vitro, while the exact function of KPNA2 in PDAC remains unclear." (PMID 33728352, 2021). "For example, KPNA2 was found to be increased in all cancer types except pancreatic cancer." (PMID 23536776, 2013).
thyroid cancer (3 papers, 2022 to 2025). "Since the role of KPNA2 in thyroid cancer is rarely reported, our findings shed light on the KPNA2-mediated ECM remodeling in ATC by transporting CREB3L1 into the nucleus." (PMID 36192735, 2022).
anaplastic thyroid carcinoma (2 papers, 2025). "In anaplastic thyroid carcinoma (ATC), abnormal ISG15 expression and ISGylation of Karyopherin Subunit Alpha 2 (KPNA2) are associated with heightened stemness and malignancy." (PMID 40103488, 2025). "Previous studies have shown that KPNA2 enhances extracellular matrix (ECM) signalling by mediating the nuclear translocation of CREB3L1, thereby promoting the growth and metastasis of anaplastic thyroid carcinoma." (PMID 40830912, 2025).
astrocytomas (2 papers, 2018). "Furthermore, the nuclear expression of KPNA2 correlated with those of NBS1 in a large series of malignant astrocytomas." (PMID 30323892, 2018).
breast tumor (2 papers, 2013 to 2022). "Despite the involvement of the Karyopherin family in breast cancer prognosis and tumorigenesis, the distinct role of KPNA2 in breast cancer outcomes and its expression patterns within breast tumour subtypes requires further investigation." (PMID 35948941, 2022). "Our analysis of patterns of KPNA2 mutations in cBioPortal and COSMIC revealed that N375S is also present in the MET gene, occurs across a range of cancer types and is detected in 9% of advanced breast tumours." (PMID 35948941, 2022). "Another gene directly co-expressed with KPNA2 is the Cell division cycle 20 (CDC20), a late mitosis checkpoint mediator that predominantly occurs in hormone positive (ER +) breast tumours (58% (N = 870), METABRIC study)." (PMID 35948941, 2022). "In breast tumor MCF7 cells, Oct4 expression was further increased by KPNA2 overexpression." (PMID 24070213, 2013).
cervical squamous cell carcinoma (2 papers, 2022). A squamous cell carcinoma arising from the cervical epithelium. "MiR-101 expression is low in cervical squamous cell carcinoma, while importin karyopherin subunit alpha 2 (KPNA2) expression is high MiR-101 suppresses the progression of cervical squamous cell carcinoma by targeting and down-regulating KPNA2." (PMID 36497343, 2022).
cholangiocarcinoma (2 papers, 2017 to 2024). A carcinoma that arises from the intrahepatic biliary tree (intrahepatic cholangiocarcinoma) or from the junction, or adjacent to the junction, of the right and left hepatic ducts (hilar cholangiocarcinoma). "In conclusion, the results of this study demonstrated that KPNA2 expression was significantly associated with poor prognosis in patients with cholangiocarcinoma." (PMID 28178675, 2017). "In the current study, nuclear KPNA2 expression exhibited a significant association with poor prognosis in cholangiocarcinoma." (PMID 28178675, 2017). "High expression levels of KPNA2 were tightly associated with recurrence in 103 patients with cholangiocarcinoma (P = 0.024)." (PMID 28178675, 2017). "In this study, overexpression of nuclear KPNA2 was significantly associated with poor prognosis and chemosensitivity of cholangiocarcinoma." (PMID 28178675, 2017). "Univariate analysis of 103 patients with cholangiocarcinoma revealed that histological type (P = 0.015), lymph node metastasis (P = 0.035), vascular invasion (P = 0.0001), perineural invasion (P = 0.017), and KPNA2 expression (P = 0.0004) were significantly associated with overall survival." (PMID 28178675, 2017). "These transcription factors may be involved in the molecular mechanism underlying reduced proliferation upon KPNA2 depletion in cholangiocarcinoma." (PMID 28178675, 2017). "In patients with cholangiocarcinoma who received gemcitabine after surgery, KPNA2 overexpression tended to be a prognostic indicator of poor overall survival." (PMID 28178675, 2017). "The significance of KPNA2 expression in cholangiocarcinoma is assumed to be consistent with the findings of previous reports." (PMID 28178675, 2017). "Depletion of KPNA2 decreased the viability of gemcitabine-treated cholangiocarcinoma cells in vitro and in vivo." (PMID 28178675, 2017). "Our data clarified the significance of KPNA2 expression in clinical cholangiocarcinoma samples and highlighted the possibility of overcoming gemcitabine resistance by targeting KPNA2 in cholangiocarcinoma cells in vitro and in vivo for the first time." (PMID 28178675, 2017). "In KPNA2-depleted cholangiocarcinoma cells, proliferation was significantly decreased and gemcitabine sensitivity was enhanced in vitro and in vivo." (PMID 28178675, 2017). "Of the 103 patients with cholangiocarcinoma, low KPNA2 expression was found in 23 (22.3%) patients and high expression in 80 (77.7%)." (PMID 28178675, 2017). "The purpose of this study was to identify the function and clinical significance of KPNA2 in cholangiocarcinoma." (PMID 28178675, 2017). "Expression of the MRN complex was colocalized with that of KPNA2 in both cholangiocarcinoma tissues and cell lines." (PMID 28178675, 2017). "KPNA2 expression in cholangiocarcinoma tissues was investigated using immunohistochemical analysis to determine whether KPNA2 expression can serve as a prognostic marker of cholangiocarcinoma." (PMID 28178675, 2017). "In this study, we clarified the significance of KPNA2 in cholangiocarcinoma." (PMID 28178675, 2017). "The present study results indicated that KPNA2 expression may be an independent prognostic marker of cholangiocarcinoma." (PMID 28178675, 2017). "Our results suggest a critical role of KPNA2 in the proliferation of cholangiocarcinoma cells." (PMID 28178675, 2017). "The regulation of KPNA2 expression may be a new therapeutic strategy for cholangiocarcinoma." (PMID 28178675, 2017). "Moreover, colocalization of KPNA2 and the MRN complex was observed in the nuclei of cells in clinical cholangiocarcinoma tissues." (PMID 28178675, 2017). "Furthermore, expression of the MRN complex was colocalized with that of KPNA2 in both cholangiocarcinoma tissues and cell lines, and cellular localization of the MRN complex was controlled by KPNA2 regulation." (PMID 28178675, 2017).
cholangiocarcinoma (continued). "However, the clinical significance of cancer-specific KPNA2 expression and the relationship with the MRN complex and gemcitabine sensitivity in cholangiocarcinoma remain unclear." (PMID 28178675, 2017).
colon adenocarcinoma (2 papers, 2013 to 2022). "We next focused on KPNA2 in colon adenocarcinoma and head/neck squamous cell carcinoma, since KPNA2 overexpression has not been reported in these two cancer types." (PMID 23536776, 2013).
COVID-19 (2 papers, 2021). A disease caused by infection with severe acute respiratory syndrome coronavirus 2. "Meanwhile, SARS-CoV-2 host genes, such as ACTB, KPNA2, and JUN, interact with SAMHD1, VCAM1, and HMOX1, in the PPI network, indicating possible mechanisms of COVID-19 associated stroke." (PMID 33732102, 2021). "Furthermore, the roles of other stroke-associated genes, such as SAMHD-1, DDAH-1, HMOX1, LTC4S, ACTB, KPNA2, and JUN, in mediating stroke secondary to SARS-CoV-2 infection are required to be further explored experimental using COVID-19 patient samples or SARS-CoV-2 animal models." (PMID 33732102, 2021).
endometrial carcinoma (2 papers, 2019 to 2023). A malignant tumor arising from the epithelium that lines the cavity of the uterine body. "Furthermore, the proliferation of oesophageal squamous cell carcinoma and endometrial cancer cells was significantly repressed by the silencing of KPNA2 using RNAi technology." (PMID 37423952, 2023).
esophageal squamous cell carcinoma (2 papers, 2013 to 2020). Esophageal squamous cell carcinoma (ESCC) is a type of esophageal carcinoma (EC) that can affect any part of the esophagus, but is usually located in the upper or middle third. "SNHG8 plays oncogenic roles in the malignancy of esophageal squamous cell carcinoma by sponging miR-411, thus increasing KPNA2 expression." (PMID 32248842, 2020).
invasive breast carcinoma (2 papers, 2019 to 2022). A carcinoma that infiltrates the breast parenchyma. "Overexpression of DCAF13, DNMT3B, KPNA2, EXO1, FANCI, RACGAP1, and ZNF106 in invasive breast carcinoma patients showed poor survival, while overexpression of CDKN2A, SORBS1, and TP63 showed better survival." (PMID 32010179, 2019).
psoriasis (2 papers, 2013 to 2021). An autoimmune condition characterized by red, well-delineated plaques with silvery scales that are usually on the extensor surfaces and scalp. "In the basal cells of psoriasis, KPNA2 expression was diffusely up-regulated in comparison to atopic dermatitis." (PMID 24098495, 2013).
urothelial carcinoma (2 papers, 2015 to 2019). A malignant neoplasm derived from the transitional epithelium of the urinary tract (urinary bladder, ureter, urethra, or renal pelvis). "KPNA2 inhibition with a specific siRNA decreased cell viability and migration and increased apoptosis in urothelial carcinoma cell lines." (PMID 25956057, 2015). "Additional in vitro experiments revealed that KPNA2 expression was higher in urothelial carcinoma cell lines than in normal urothelial cell line." (PMID 25956057, 2015). "KPNA2 expression in normal urothelial cell line and urothelial carcinoma cell lines was evaluated by western blot analysis." (PMID 25956057, 2015). "Taken together, these data show that KPNA2 knockdown activated the apoptosis pathway and decreased the proliferation of urothelial carcinoma cells." (PMID 25956057, 2015). "Additionally, KPNA2 knockdown resulted in decreased cell proliferation and migration and increased apoptosis in urothelial carcinoma cells." (PMID 25956057, 2015). "Additionally, the role of KPNA2 in the proliferation, migration and apoptosis of urothelial carcinoma cell lines was analyzed in vitro." (PMID 25956057, 2015).
actinic keratosis (1 paper, 2013). A precancerous lesion of the skin composed of atypical keratinocytes. "In malignant cells of SCC in situ such as Bowen’s disease and actinic keratosis as with well prognosis, KPNA2 expressed predominantly in the basal layer." (PMID 24098495, 2013). "Comparing Bowen’s disease and actinic keratosis, which are known as SCC in situ, KPNA2 was remarkably and diffusely overexpressed." (PMID 24098495, 2013).
Alzheimer disease (1 paper, 2021). A progressive, neurodegenerative disease characterized by loss of function and death of nerve cells in several areas of the brain leading to loss of cognitive function such as memory and language. "Accumulation and aggregation of KPNA2 is found in neurofibrillary tangles and Hirano bodies of hippocampal CA1 neurons of Alzheimer’s disease patients." (PMID 34019093, 2021).
atopic dermatitis (1 paper, 2013). "In contrast, very few but significant numbers of KPNA2-positive keratinocytes were observed in the basal lesions of atopic dermatitis, particularly in the inflamed proliferating lesions." (PMID 24098495, 2013).
benign bone tumors (1 paper, 2020). "All samples from benign bone tumors including osteoid osteomas, osteochondromas and chondroblastomas were negative for KPNA2." (PMID 33176814, 2020). "Negative KPNA2 expression was observed in all benign bone tumors." (PMID 33176814, 2020).
bladder tumors (1 paper, 2015). "In our study, KPNA2 immunoreactivity was demonstrated to be a prognostic factor for bladder recurrence of primary UTUC after RNU in the multivariate Cox regression analysis after excluding patients with bilateral synchronous UTUCs and those with previous or concomitant bladder tumors." (PMID 25956057, 2015).
bone tumors (1 paper, 2020). "Karyopherin α2 (KPNA2), a member of the karyopherin α family, has been studied in several cancers but has not yet been substantially investigated in malignant bone tumors." (PMID 33176814, 2020). "However, in human malignant bone tumors, the expression level of KPNA2 has not been clarified." (PMID 33176814, 2020).
cardiomyopathy (1 paper, 2014). A disease of the heart muscle or myocardium proper. "Therefore, since KPNA2 is involved in the transport of molecules under a wide variety of cell conditions, it could be relevant in ICM taken into account the stress conditions that exists in this cardiomyopathy." (PMID 25137373, 2014).
Cirrhosis (1 paper, 2020). A chronic disorder of the liver in which liver tissue becomes scarred and is partially replaced by regenerative nodules and fibrotic tissue resulting in loss of liver function. "We finally selected three upregulated hub genes (KPNA2, TARBP1, and RNASEH2A) for which expression was systematically increased from normal liver to cirrhosis and HCC tissues based on the GSE89377 dataset." (PMID 32213663, 2020).
diabetic kidney disease (1 paper, 2026). Progressive kidney disorder caused by vascular damage to the glomerular capillaries, in patients with diabetes mellitus. "In diabetic kidney disease, a hyperglycemic environment upregulates SLC1A5 expression via KPNA2, activating the mTORC1/p70S6K pathway to inhibit autophagy." (PMID 41601931, 2026).
ductal breast carcinoma (1 paper, 2022). "Genes most frequently co-expressed with KPNA2 in ductal breast carcinoma were found to be least expressed in healthy breast tissue." (PMID 35948941, 2022).
dysgerminoma (1 paper, 2012). A malignant germ cell tumor characterized by the presence of a monotonous primitive germ cell population. "QRT-PCR assay determined the expression level of KPNA2 in dysgerminomas, yolk sac tumors, mixed ovarian germ cell tumors, and immature teratoma as 4.13 times, 2.11 times, 2.66 times and 3.5 times higher pronounced than normal ovarian specimens, respectively." (PMID 22962582, 2012). "Extensive KPNA2 expression was observed in 3/3 dysgerminomas, 4/6 yolk sac tumors, 7/9 immature teratomas and 4/4 mixed ovarian germ cell tumors (mixed with yolk sac tumors and embryonal carcinomas), and 1/1 embryonal carcinoma." (PMID 22962582, 2012). "QRT-PCR data supported the observation of extensive KPNA2 expression in several common pathological types of OMGCTs including yolk sac tumors, immature teratomas, dysgerminomas, mixed ovarian germ cell tumors and embryonal carcinoma when compared with normal ovarian tissues." (PMID 22962582, 2012). "Immunohistochemistry confirmed that increased KPNA2 protein expression was presented in yolk sac tumors, immature teratomas, dysgerminomas, embryonal carcinomas, and mixed ovarian germ cell tumors, whereas negative KPNA2 expression was observed in all normal ovarian specimens." (PMID 22962582, 2012).
head-neck cancers (1 paper, 2013). "For the first time, the cancer-specific up-regulation of KPNA2 and its clinical significance were verified by tissue microarray analysis in colon and head-neck cancers." (PMID 23536776, 2013).
invasive ductal carcinoma (1 paper, 2022). "KPNA2 amplification occurred in patients with invasive ductal carcinoma and was more frequently observed in patients with oestrogen-receptor negative breast cancer." (PMID 35948941, 2022). "We also compared KPNA2 expression profiles across different breast cancer subtypes that included carcinoma, invasive ductal carcinoma and adenocarcinoma." (PMID 35948941, 2022). "Furthermore, KPNA2 mRNA expression levels were found to be significantly amplified in patients with invasive ductal carcinoma." (PMID 35948941, 2022).